RNU6-393P (RNA, U6 small nuclear 393, pseudogene)
Gene: Small nuclear RNA gene on chromosome 7 (98,794,718 to 98,794,824, reverse strand). Ensembl gene ENSG00000207204.
Homologues: Orthologues: chimpanzee U6 (99% identical), mouse Gm26501 (94% identical). Paralogues in human: RNU6-1145P (95% identical), RNU6-16P (95% identical), RNU6-25P (95% identical), RNU6-29P (95% identical), RNU6-35P (95% identical), RNU6-41P (95% identical), RNU6-1 (94% identical), RNU6-15P (94% identical), RNU6-2 (94% identical), RNU6-20P (94% identical), RNU6-39P (94% identical), RNU6-3P (94% identical), and 1287 more.